TAP2 (transporter 2, ATP binding cassette subfamily B member)
Diseases named in the same sentence as TAP2 in open-access papers (continued):
Sharing a sentence is not in itself a finding about the gene and the disease.
cancer (continued). "Other dMMR/MSI‐associated immune escape mutations that varied in frequency between cancer types included RPL22, which was enriched in EC, and the antigen processing and presentation pathway components B2M, NLRC5, TAP2, and HLA‐B, which were more commonly disrupted in CRC." (PMID 35262923, 2022). "The downregulation of ß2-m,TAP1, TAP2, LMP7, ERAP1, tapasin, and ERp57 protein expression positively associated with HLA-I expression in CIN lesions, whereas ß2-m, TAP1, TAP2, LMP2, LMP7, ERAP1, ERp57, and tapasin expression positively associated with HLA-I in the cancerous lesions." (PMID 23024775, 2012). "TAP-1 and TAP-2 down-regulation in general will lead to a reduced efficiency in antigen presentation and immune-responses and is considered as an important mechanism of cancer immune-escape." (PMID 20865050, 2010). "Similarly, using RNA-seq data, we found that a lower expression of APM-related genes, including B2M, CIITA, ERAP2, TAP2 and TAPBPL, was also associated with a shorter PFS, reflecting the increasing interest in APM biomarkers for clinical outcome and immune escape in cancer." (PMID 37799721, 2023). "Specifically, TAP1, TAP2, TAPBP, PSMB8, and CALR were significantly upregulated in 17, 14, 13, 15, and 15 distinct cancer types, respectively." (PMID 38297270, 2024). "Of these genes, TAP2, B2M, IRF1, TAP1, HLA-A, HLA-B and HLA-C were formally and independently classed as CRC drivers, with strongest signals in MSI cancers, but also discovered in MSS cancers (for example, HLA-A and B2M)." (PMID 39112709, 2024). "The NPS was significantly and positively associated with HLA genes, including TAP1, HLA-E, HLA-DRA, B2M, TAP2, HLA-DPA1, and HLA-DOA in all cancers." (PMID 36170029, 2022). "Results showed MHC genes, including TAPBP, TAP1, and TAP2, were highly positively correlated with FANCE in most cancers." (PMID 36685883, 2022). "The increased expression of TAP1, TAP2, Tapasin was also observed in colorectal CT26 cancer cells treated with 10 μM ACB-1801." (PMID 36458012, 2022). "It was then disclosed that TAP2, LMP2, and LMP7 expression often declined in HPV+ cancer and that decreased LMP7 expression and medium/high nuclear LMP10 staining correlated with better survival in HPV+ cancer." (PMID 34069114, 2021). "On Western blot analysis with lysates from cultured cell lines, HLA-HC, β2 microglobulin, tapasin, TAP-1, TAP-2, LMP-7, and LMP-10 expressions differed among the cancer cell lines." (PMID 22134332, 2012). "There was a different expression pattern among cancer cell lines for HLA class I heavy chain (HLA-HC), β2 microglobulin, Tapasin, TAP-1, TAP-2, LMP-7 and LMP-10." (PMID 22134332, 2012). "In addition, we knocked down TAP2 and MED12 in cancer cells, and then co-cultured these cancer cells with CD8 + T cells, and quantified lactate dehydrogenase (LDH) levels to assay T cell cytotoxicity, as a consequence of antigen processing and presentation." (PMID 40888963, 2025). "One notable aspect of our results is the prominent difference in the frequency of TAP1 and TAP2 cancer cell downregulation in NSCLC, as well as their dissimilar impact on surface antigenic peptide abundance and role in protection of cancer cells from T-cell attack." (PMID 40091029, 2025). "Most tumors showed comparable levels of TAP1 and TAP2 protein in both CK-positive cancer cells and in CK-negative (non-malignant) stromal cells." (PMID 40091029, 2025). "The transporter associated with antigen processing (TAP) plays a critical role in peptide delivery, and cancer cells can modulate TAP1 and/or TAP2 levels to reduce peptide delivery, thereby evading recognition by cytotoxic CD8+ T cells (El Hage, Durgeau & Mami-Chouaib, 2013)." (PMID 37483962, 2023). "Surprisingly, almost all major histocompatibility complex molecules (MHCs), except TAP2, were negatively correlated with FASN expression in a variety of malignancies, especially in LGG, when we examined the correlation between FASN expression and MHCs in pan-cancer." (PMID 36555243, 2022).
cancer (continued). "In addition, CCNA2 could positively regulate TAP1, TAP2, CD276, MICB, PVR, and ULBP1 in almost all the cancer types." (PMID 35401923, 2022). "When the expression of MHC I pathway genes was analyzed by qPCR, we found reductions in transcripts of TAP1, TAP2, and ERAP1 genes (other MHC I pathway genes were not examined), which was consistent with our earlier studies with other cancers." (PMID 39354629, 2024). "Moreover, the expression levels of TAP1 and TAP2, another two molecules essential for MHC-I-mediated antigen presentation, are also relatively higher in responders than non-responders in CRC and many other cancers." (PMID 36551849, 2022).
infection (16 papers, 2010 to 2025). The state of being infected such as from the introduction of a foreign agent such as serum, vaccine, antigenic substance or organism. "The majority of genes (CTNNB1, MARCO, STAT5a/b, TAP1, and TAP2) that regulate proliferation and differentiation of immune cells showed a differential higher expression in KO and SP-A variants in response to infection." (PMID 32670284, 2020). "Besides, the transporter associated with antigen processing (TAP, TAP1, TAP2) and most MHCs showed a decrease in expression at 28, 38 h post-YC-2020 infection, with a stronger downtrend than the JXA1 group." (PMID 36338035, 2022). "It was only reported that the TAP2 gene in grass carp were up regulated in the spleen and kidney after infection with A. hydrophila." (PMID 39450165, 2024). "We also observed the upregulation of DEGs related to antigen presentation such as Tap1 and Tap2, in particular during infection with NF1_LV, suggesting the activation of the adaptive immune system." (PMID 39735262, 2024). "Regarding the presence of HPV, carriers of the wild-type genotype for all SNPs studied in homozygosis showed increased expression of mRNA and TAP-2 protein as part of the elaboration of the immune response to the infection." (PMID 36619767, 2022). "Analysis of the vessel data revealed several proteins related to the acute-phase response to infection (Hp, Hpx, Serpina3n, Fga/b, Igfbp7, Cfh, and C4b), antigen presentation (Tap1, Tap2, Tapbp, H2-D1, and H2-Q10), and interferon response (Igtp, Gbp2, Irgm1, and Iigp1)." (PMID 32843537, 2020). "Among the three peptide transporters identified, an increased expression was observed in TAP1 and TAP2 genes in cells infected with the mutant virus, while a higher expression was recorded for TAPBP during infection with the WT virus." (PMID 37513744, 2023). "The transcript abundance of B2M, MHC class I antigen 2 (SLA-2), SLA-3, TAP2, and chaperones (such as GRP78) was markedly increased after infection with N-PRRSV while the transcript abundance of SLA-B was significantly decreased." (PMID 20614006, 2010). "However, in response to infection, male mice exhibited higher expression levels of CDKN1B, and CTNNB1 (KO, 1A3), TCF4 (1A0, 6A2), TAP1, and TAP2, (1A0), CDKN1A, (1A3, 6A2), MARCO, and MMP12 (1A3), CCND1, CDK2, IRF and MYC (6A2) compared to females." (PMID 32670284, 2020). "Importantly, infection with Ad5-IFNγ induces TAP1 and TAP2 expression in the RM-1 cell lines." (PMID 23056548, 2012). "Furthermore, increased levels of TAP-transporters (TAP1, TAP2), MHC I components B2M and HLAs, together with the ER chaperons calreticulin (CALR) and calnexin (CALN), and aminopeptidases ERAP1 and ERAP2 indicated upregulation of MHC I dependent antigen presentation with progressing infection." (PMID 37112941, 2023).
adenocarcinoma (2 papers, 2021 to 2025). A common cancer characterized by the presence of malignant glandular cells. "In the analysis of clinicopathologic variables, cases with low TAP1 showed no consistent associations and TAP2 downregulation was more frequent in tumors with squamous cell histology than in adenocarcinomas." (PMID 40091029, 2025).
bacterial infections (1 paper, 2019). "Notably, the human antigen peptide transporter 2 (TAP2) gene has been previously reported to be up-regulated during bacterial infections." (PMID 31881845, 2019).
TAP2 also shares sentences with these, for which no sentence is quoted: infectious disease (3 papers); ankylosing spondylitis (2); celiac disease (2); cervical neoplasm (2); Graves disease (2); influenza (2); non-small cell lung carcinoma (2); rheumatoid arthritis (2); serous ovarian cancer (2); vitiligo (2); AIDS (1); allergies (1); Alzheimer disease (1); atopic asthma (1); autoimmune thyroiditis (1); Bare-Lymphocyte syndrome (1); benign tumors (1); breast tumor (1); central nervous system demyelinating disease (1); cervical intraepithelial neoplasm (1); Childhood onset (1); childhood onset asthma (1); colorectal (1); combined immunodeficiency (1); dermatitis (1); diabetes (1); diffuse large B-cell lymphoma (1); Epstein-Barr virus infection (1); esophageal squamous cell carcinoma (1); Ewing sarcoma (1).
A further 36 diseases each share a sentence with TAP2 in 1 paper.